HSF1 (heat shock transcription factor 1)
Diseases named in the same sentence as HSF1 in open-access papers (continued):
Sharing a sentence is not in itself a finding about the gene and the disease.
tumor (continued). "Indeed, knockdown of Hsf1 prevents neoplastic transformation (foci formation or tumor growth in xenografts) induced by HER2 expression in untransformed human mammary epithelial MCF-10A cells." (PMID 24212658, 2011). "This suggests that Adel55 could replicate efficiently in HSF1 overexpression tumor tissue, which is consistent with the in vitro result." (PMID 20459615, 2010). "Induction of HSPs by HSF1 is essential for the growth of many tumor cells." (PMID 20537126, 2010). "We found Adel55 could replicate more efficiently and mediate more effective cytotoxicity in tumor cells with higher level of HSF1 activity." (PMID 20459615, 2010). "Our results showed that this constitutive HSF1 mutant (cHSF1) overexpression could dramatically increase the replication of Adel55 in tumor cells and enhance the antitumor efficacy of Adel55 in vitro and in vivo." (PMID 20459615, 2010). "To test our hypothesis, we employed four tumor cell lines of different origins and tested the effect of different HSF1 activity on the oncolytic effect of an E1B55kD gene deleted oncolytic adenovirus Adel55 constructed by our lab." (PMID 20459615, 2010). "This further demonstrated that Adel55-cHSF1 could lead to overexpression of HSF1 in tumor tissues and then enhance the replication of Adel55 to kill the tumor cells more efficiently." (PMID 20459615, 2010). "We hypothesized that the different cytotoxicity of Adel55 to different tumor cell lines might correlate to their different HSPs transcription level by HSF1." (PMID 20459615, 2010). "Due to the inherently high proteotoxic stress in the tumor derived cells, inhibition of HSF1 induction might be a way to counteract the induction of unfolded protein response and avoid apoptosis; a feature that might be necessary for the cell survival." (PMID 19337383, 2009). "Elevated HSF-1 levels drive metastasis by suppressing antimetastatic gene expression and activating pro-metastatic signaling pathways, including the upregulation of metastasis-associated protein 1 (MTA-1), which interferes with oestrogen-mediated tumor suppression." (PMID 41375025, 2025). "Thus, HSF1 affects multiple traits of the tumor cell, not limited to tumor proliferation." (PMID 39243039, 2024). "Thus, CsA, via the inhibition of HSF1 through phosphorylation, could be used as chemotherapy to decrease tumor progression." (PMID 39433125, 2024). "Furthermore, HSF1 seems to be involved in drug resistance of tumor cells mediated by macrophages." (PMID 39243039, 2024). "HSF1 expression was significantly elevated in each pathological stage of the HNSCC patients compared to the adjacent normal tissues, and the results indicated that the high expression of HSF1 was associated with the advanced tumor stage of patients and relatively high lymph node metastasis." (PMID 37686660, 2023). "Collectively, we uncovered that hyperactive USP14 contributed to HNSCC tumor growth and lung metastasis by reinforcing HSF1-depedent HSP activation, and our findings provided the insight that targeting USP14 could be a promising prognostic and therapeutic strategy for HSNCC." (PMID 37686660, 2023). "Unexpectedly, HSF1 could affect tumor immunity by regulating MHC-I machinery or PD-L1 expression." (PMID 36010849, 2022). "Collectively, these results revealed that HSF1 may be involved in tumor immune regulation." (PMID 35006040, 2022). "Considering the role of HSF1 in tumor development, HSF1 could be a potential therapeutic target." (PMID 36036010, 2022). "Importantly, in tumours from TNBC patients, DYRK2 levels positively correlate with active HSF1 and associates with poor prognosis, suggesting that DYRK2 could be promoting TNBC." (PMID 33268814, 2021). "Furthermore, HSF1 can improve the tumor microenvironment to promote its survival." (PMID 34107992, 2021). "Furthermore, our data suggest that nuclear DYRK2 might be the pool responsible for its HSF1-dependent tumour promoter role in TNBC." (PMID 33268814, 2021).
tumor (continued). "In addition, higher levels of HSF1 mRNA found in tumor biopsies from a wide range of disease types may indicate a role for the expression of the factor in tumor morbidity." (PMID 32331382, 2020). "Thus, in this study, we explore whether HSF1 expression is associated, similarly to that of HOP in GC, with an advanced tumour stage and poor prognosis." (PMID 30326922, 2018). "Importantly, the radiosensitization of tumor cell by the Hsp90 activity inhibitors can be significantly enhanced by preventing the induction/up-regulation of Hsp70 that is possible to render with known inhibitors of HSF1." (PMID 28291803, 2017). "Although activation of HSF1 might be beneficial for the survival of normal cells, it is plausible to hypothesize that its aberrant activation plays a role in carcinogenesis by protecting tumor cells from stress-induced death." (PMID 28903330, 2017). "Hence, we sought to rank individual HSF1-CanSig 8q genes in different primary tumor sites." (PMID 29268782, 2017). "In addition, HSF1 knockdown reduces the invasiveness of multiple types of tumor cells." (PMID 27997575, 2016). "It is known that HSF1 activation is a key factor in the transcriptional reprogramming of the stroma from a tumor-repressive environment to a supportive one by upregulating genes that promote the malignant phenotype and by downregulating genes that might trigger an anticancer immune response." (PMID 26511079, 2015). "Additionally, we observed that high expression of HSF1, whether in tumor cells or in stromal cells, was an independent predictor of DFS and OS in patients with metastatic ESCC, but not locoregional ESCC." (PMID 26511079, 2015). "Thus, this cooperation may account for the better outcome of ESCC patients with low levels of HSF1 activation both in stromal cells and tumor cells." (PMID 26511079, 2015). "In addition, knockdown of HSF1 with siRNA may induce human tumor cell apoptosis in vitro, which supports the evidence that HSF1 has important roles in maintaining tumor development." (PMID 25199534, 2014). "In addition, HSF1 is a potent factor supporting tumor growth." (PMID 24467529, 2014). "Our previous study showed that constitutively active heat shock transcription factor 1 (cHSF1) expression could dramatically increase the replication of the replication competent adenovirus Adel55 in tumor cells and enhance the antitumor efficacy of Adel55 in vitro and in vivo." (PMID 22613625, 2012). "Furthermore, inhibition of HSF1 leads to the induction of cell death and tumor regression." (PMID 20537126, 2010). "Research published in Nature Cell Biology revealed that in TME, activation of HSF1 in NK cells leads to a decrease in the expression of effector molecules, such as NK1.1 and IFNγ, thereby impairing their cytotoxic function against tumor cells." (PMID 40287736, 2025). "HSF1 deletion leads to a downregulation of HuR resulting in impaired HIF-1-α translation, thereby hindering tumor angiogenesis." (PMID 40287736, 2025). "Specifically, increased ROS production under hypoxia conditions activates HSF1 and HSP70, promoting the expression of Siglec-5 and Siglec-14, which in turn affects immune cell functions and tumor progression." (PMID 40858654, 2025). "Promising approaches such as targeting SPARC-mediated nanoparticle uptake, HSF1 and TGF-βRII signaling, or CAF-derived exosomal miRNAs, offer innovative avenues to disrupt tumor–stroma crosstalk." (PMID 41583435, 2025). "By disrupting HSF1 activity, NXP800 induces an unfolded protein response, leading to proteotoxic stress, suppression of AR activity, and ultimately, inhibition of tumor growth." (PMID 41235005, 2025). "The deletion of HSF1 reduced tumorigenesis and metastasis in ERBB2 overexpressing cells, decreasing tumor growth rate and suppressing angiogenesis." (PMID 40287736, 2025).
tumor (continued). "Combination of HSF1 and CBS knockout decreases tumor size for a small cell PCa xenograft mouse model." (PMID 38172561, 2024). "Specifically, the highest levels of HSF1 characterized KKU-M156 and RBE iCCA cells, whereas lower levels (but still higher than in hCAFs) were found in HuCCT1 tumor cells." (PMID 39243039, 2024). "The activation of HSP results in the stabilization of several tumor‐promoting HSP clients such as AKT, mTOR and HSF1 itself, which substantially accelerates tumor development." (PMID 39049197, 2024). "HSF1 regulates MYCN transcription by binding to both its promoter and SE regions, thereby promoting tumor cell growth." (PMID 39248163, 2024). "Demonstrating the translational potential of HSF1 inhibition, combined therapy of mEHT with KRIBB11 significantly reduced tumor mass compared to either monotherapy." (PMID 38589452, 2024). "The suppression of CCL5 expression by heat shock Factor 1 (HSF1) prevents CD8+ T-cell influx, which supports immune-mediated tumor killing." (PMID 38928033, 2024). "In animal models, KRIBB11 demonstrated HSF1 inhibitory effects, lowering HSP70 expression and tumor volume." (PMID 38339390, 2024). "Further, HSF1 knockdown leads to downregulation of major histocompatibility class I chain-related proteins B (MICB), a natural killer cell‐activating ligand on tumor cells, and decreased NK cell cytotoxicity." (PMID 37153737, 2023). "In this study, we screened 19 genes associated with ferroptosis, of which 10 FerDEGs such as TLR4, KRAS and HSF1 were highly expressed and 9 FerDEGs such as MUC1, PROM2 and MT1G were lowly expressed in tumour tissue." (PMID 36936437, 2023). "We had observed this correlation previously at protein levels wherein nuclear DYRK2 expression positively correlated with nuclear HSF1 and this dual expression predicted poor patient prognosis in TNBC tumour samples." (PMID 36622366, 2023). "These experiments illustrate the importance of both DYRK2 and HSF1 for TNBC tumour growth and further show that DYRK2 plays a major role in the growth of HSF1-proficient tumours." (PMID 36622366, 2023). "IHC staining for HER2, HSF1, and EGR4 in tumour punch biopsies revealed the positive nuclear staining of HSF1 and EGR4 in tumours presenting with positive membrane staining for HER2 across 15 tumour samples." (PMID 35326716, 2022). "HER2 overexpression promotes the activation of the HSF1-Hsp90 axis and the stabilization of Hsp90 client proteins, such as MIF, AKT, and mTOR, leading to increased tumor growth." (PMID 35887137, 2022). "Latest study reported that HSF1 is also essential for extracellular matrix remodeling in CRC by CAF, highlighting HSF1 vital roles in regulating tumor microenvironment." (PMID 35006040, 2022). "By regulating a series of proteins, HSF1 and HSP can aggravate the deterioration of tumor cells, make tumor cells grow and proliferate, and promote the expression of tumor cell genes and proteins." (PMID 34539881, 2021). "A study conducted by Grunberg suggested that HSF1 upregulated inhibin subunit beta A (INHBA) and thrombospondin 2 (THBS2), which are involved in tumor progression." (PMID 34064083, 2021). "The master transcriptional determinant HSF-1 plays a pleiotropic role not only in regulating the HSR, but also during tumorigenesis, tumor cell migration, and metastasis." (PMID 34775489, 2021). "Subcutaneous tumor formation models were established by co-implanting CAFs and GBC cells or GBC cells overexpressing heat shock factor 1 (HSF1) to evaluate the roles of TSP-4 and HSF1 in vivo." (PMID 33407730, 2021). "The knockdown efficiency was confirmed by the reduced protein levels of HSF1 and HSP27 in tumor tissues." (PMID 33675143, 2021).
tumor (continued). "Similar to the in vitro results, celastrol and erastin cotreatment also increased the expression of LC3‐II, Parkin, HSF1, and HSP27 in tumor tissues." (PMID 33675143, 2021). "This link between DYRK2 and HSF1 is also observed in TNBC tumor samples, wherein a marked correlation was observed between high DYRK2 levels and high nuclear HSF1 levels." (PMID 33376136, 2021). "Together, these observations describe a positive feedforward loop, in which HSF1 and TGF-β induce the expression of the other factor in tumor cells and CAFs." (PMID 32331382, 2020). "Heat shock transcription factor 1 (HSF1), a member of the HSF family of transcription factors, regulates abnormal signals of tumour cells and promotes metastasis and metabolism of BC tumour cells." (PMID 32964046, 2020). "Interestingly, even if HSF1 activation occurred in cancer-associated fibroblasts (non-cancerous cells in the tumor microenvironment), it was accompanied by EMT induction in oral squamous cell carcinoma cells, which, as a result, enhanced their migration and invasiveness." (PMID 32268506, 2020). "HSF1 and HSP70 are already overexpressed in tumor cells under physiological conditions, and therefore, RT exacerbates the therapy resistance in the vicious manner." (PMID 31878360, 2019). "This work reveals an unpredicted link between HSF1, Wnt signalling and YAP/TAZ relevant for the generation of tumour-promoting CAFs." (PMID 30631061, 2019). "The reproducibility of the tumor onset and progression in the genetically engineered KPC mouse model has allowed us to explore how AMPK and HSF1 affect the progression of PDAC." (PMID 28783244, 2017). "After siRNA-mediated silencing of HSF1 in ASPC-1 and PANC-1 cells, tumor cell proliferation was evaluated in CCK-8 assays." (PMID 28482903, 2017). "HSF1 regulates the activation of PKC and its downstream signaling pathway to inhibit tumor cell apoptosis." (PMID 28482903, 2017). "In this study, we revealed that the expression of HSF1 was increased in both fibroblast cells and ESCC cells by the interaction in the tumor microenvironment." (PMID 26511079, 2015). "To investigate the expression of HSF1 in human ESCC tissues, we examined the expression of HSF1 in tumor tissues and matched normal adjacent tissues from eight ESCC patients by western blotting and real-time PCR analysis." (PMID 26511079, 2015). "The present study investigated HSF1 protein expression and its phosphorylaton at S326 in HCC tumor tissues and HCC cell lines." (PMID 25199534, 2014). "Although HSF1 is not considered to be a tumor suppressor or a typical oncogene, it influences signaling pathways associated with oncogenic hallmarks including growth, proliferation, apoptosis, metabolism, angiogenesis or cell motility." (PMID 40287736, 2025). "This could be a method by which HSF1 and MYC affect metabolism to support their functions in tumor cells." (PMID 39831777, 2025). "In addition, HSF1 promoted cell migration and EMT, which are critical steps in tumor cell invasion and metastasis." (PMID 40981348, 2025). "To further assess whether active PLK1 was associated with MYC or HSF1 in primary samples of patient with HGSOC, we performed IHC for active PLK1 (pT210), HSF1, and MYC using 58 tumor samples of patients with HGSOC." (PMID 39831777, 2025). "Notably, FBXW7, a well-established tumor suppressor gene, downregulates HSF1 expression upon overexpression, indicating that FBXW7 acts as a tumor suppressor in PCa cells by negatively regulating HSF1." (PMID 41154598, 2025). "Given HSF1’s truly multifaceted role, it comes as no surprise that it also influences tumor microenvironment (TME)– a space consisting of various cell types, extracellular vesicles (EVs) and signal molecules." (PMID 40287736, 2025). "We also showed here that the negative effects of increased HSF1 activation in tumor cells, observed after their co-culture with monocyte-like cells, can be neutralized by the HSF1 activity inhibitor CL-43." (PMID 38280079, 2024).
tumor (continued). "Another way by which HSF1 helps tumor cells to evade immune surveillance is by suppressing the expression of CCL5, a CD8+ T-cell chemokine, thereby inhibiting the recruitment and infiltration of CD8+ T-cells into the tumor microenvironment." (PMID 39682216, 2024). "HSF1 remained largely unchanged but this is not surprising due to the already ongoing stress response facilitating growth of these tumor cells." (PMID 36869047, 2023). "In addition, it is important to consider that HSPs (HSP27, HSC70, HSP70, HSF1 and HSP90) expression is altered in normal and tumor cells exposed to different stressors (pharmacological, hypoxic, thermal and oxidative)." (PMID 36997813, 2023). "Using HSF1 and/or HSF2 knockout cell lines, dysregulated responses to nutrient stress could be observed, as well as a reduction in tumor progression, making HSF2 a critical co-factor of HSF1." (PMID 36765939, 2023). "In addition to the different levels of chaperones that are dependent on HSF1, the inflammatory response mediated by AP1 and ATF3 (regulated by HSF1) can differ from tumor to tumor." (PMID 36010586, 2022). "Based on these results, inhibition of Hsp70 alone did not seem to be a promising strategy, so, to overcome tumor cell resistance to anticancer drugs, we used an HSF1 inhibitor that is able to reduce the expression of Hsp90, Hsp70, and Hsp 40 simultaneously." (PMID 35893747, 2022). "To determine whether emetine suppressed the growth of PC9-ErlR tumors through the inhibition of HSF1 in vivo, we measured the protein levels of HSF1, EGFR, HSP27, and MCL1 in tumor tissues of emetine- and control-treated mice." (PMID 34203709, 2021). "Further investigations revealed that several pathways, such as inhibition of the self-renewal of cancer stem cells/tumor-initiating cells through NOTCH1 activation and downregulation of heat shock factor 1 (HSF1), thereby increasing tumor cell apoptosis, are involved in the process." (PMID 34204214, 2021). "Indeed, many of the HSP90 activity inhibitors stimulate the HSF1 activation-mediated induction of HSP70, HSP27 and MDR1, which can elevate the radioprotective and adaptive potential of the tumor cells that survived after the inhibitory treatment." (PMID 33806538, 2021). "In addition, we proved the efficacy of HSF1 inhibitors to induce apoptosis of several EGFR-TKI-resistant cell lines in vitro and to inhibit the tumor growth of PC9-ErlR cells in vivo." (PMID 34203709, 2021). "The function of HSF1 and its impact on the tumor immune microenvironment were not fully investigated." (PMID 34239690, 2021). "Our comprehensive analysis of mouse colons at different time points along inflammation and tumor progression portrays dynamic temporal changes in ECM structure and composition, most of which are HSF1-dependent, and many of which precede the appearance of tumors." (PMID 33288768, 2020). "In fact, the mouse macrophage tumor cell line P388D1 displayed heat-induced thermotolerance in the absence of HSF1 transactivation capacity and subsequent HSP induction." (PMID 32290618, 2020). "Although transient activation of HSF1 and NRF2 is undoubtedly broadly cytoprotective, their persistent activation may promote tumor progression and chemoresistance." (PMID 31052524, 2019). "Due to the critical roles of AKT and HSF1 in tumor progression, we hypothesized that dual inhibition of both AKT and HSF1 would show synergistic efficacy." (PMID 29088759, 2017). "Additionally, when AKT activity signature scores were calculated for each tumor, a significant correlation was observed between AKT activity and expression of these HSF1 target genes." (PMID 29088759, 2017). "No single primary tumor site had all 29 HSF1-CanSig 8q genes overexpressed in the top 100 HSF1-CanSig genes." (PMID 29268782, 2017). "Since X66 does not induce HSR, we were interested to find out whether its combination with HSF-1 activators, such as GM, MG132 or celastrol, has potential effect on anti-tumor activity." (PMID 27105490, 2016).